GNRH1 (gonadotropin releasing hormone 1)
Description:
Stimulates the secretion of gonadotropins; it stimulates the secretion of both luteinizing and follicle-stimulating hormones.
Synonyms: GNRH; GRH; LHRH; LNRH
Tractability: Antibody: its Gene Ontology location is reachable by antibodies, with high confidence; UniProt places it where antibodies can reach, with medium confidence; UniProt predicts a signal peptide or a membrane-spanning region.
Gene: Protein-coding gene on chromosome 8 (25,419,258 to 25,424,654, reverse strand). Ensembl gene ENSG00000147437.
Subcellular location: Secreted
Pathways (Reactome):
Signal Transduction: G alpha (q) signalling events; Hormone ligand-binding receptors
Gene Ontology:
Molecular function: gonadotropin hormone-releasing hormone activity; gonadotropin-releasing hormone receptor binding; hormone activity
Biological process: cell-cell signaling; regulation of signaling; signal transduction; estrous cycle; female pregnancy; male sex determination; negative regulation of apoptotic process; negative regulation of immature T cell proliferation; ovulation cycle; response to lipopolysaccharide; response to peptide hormone; response to potassium ion; response to prolactin; response to prostaglandin E; response to testosterone
Cellular component: extracellular region; axon terminus; cytoplasmic side of rough endoplasmic reticulum membrane; dendrite; Golgi-associated vesicle; neurosecretory vesicle; perikaryon
Genetic constraint (gnomAD): Loss-of-function variants: 2 observed, 5.11 expected, observed/expected ratio (o/e) 0.39, 90% interval 0.16 to 1.22. That is too few expected variants to judge how well the gene tolerates losing a copy. Missense variants: 45 observed, 40.47 expected, observed/expected ratio (o/e) 1.11, 90% interval 0.88 to 1.43. Synonymous variants: 11 observed, 14.38 expected, observed/expected ratio (o/e) 0.76, 90% interval 0.48 to 1.27.
Homologues: Orthologues: chimpanzee GNRH1 (98% identical), macaque GNRH1 (92% identical), rabbit GNRH1 (80% identical), guinea pig GNRH1 (76% identical), dog GNRH1 (75% identical), pig GNRH1 (73% identical), mouse Gnrh1 (72% identical), rat Gnrh1 (72% identical), tropical clawed frog gnrh1 (42% identical), zebrafish gnrh3 (24% identical). Paralogues in human: GNRH2 (20% identical).
Diseases named in the same sentence as GNRH1 in open-access papers:
GNRH1 is named in the same sentence as 503 diseases in open-access papers, as found by Europe PMC text mining. Sharing a sentence is not in itself a finding about the gene and the disease. The quoted sentences say what the papers report.
Infertility (311 papers, 2005 to 2026). "In mice and humans, natural homozygous mutations in the GNRH1 gene result in hypogonadal hypogonadism and infertility due to a significant decrease in FSH and LH circulating levels." (PMID 35628411, 2022). "Failure of GnRH neuron migration and maturation and dysregulation of Gnrh1 gene expression have been implicated in the incorrect timing of puberty, reproductive deficiencies, and infertility." (PMID 27389022, 2016). "Our current results differ from previous studies in mice, where homozygous natural mutation in GnRH1 resulted in hypogonadal hypogonadism caused by insufficient LH and FSH circulation, which led to infertility in all individuals." (PMID 35628411, 2022). "In 1986, Mason and colleagues demonstrated that hpg mice, which completely lack GnRH due to a truncating deletion in Gnrh1, are sexually immature and infertile." (PMID 34502334, 2021). "Likewise, adult Rank deletion led to lower hypothalamic amounts of mRNA of Gnrh1 and Rank and induced hypogonadism, reflected by reduced testicular weight and infertility in half of RankiUbcΔ/Δ mice." (PMID 41818388, 2026). "GNRH1 displayed mutations in five of eight infertile men and one of two fertile controls, however this was not validated with Sanger sequencing." (PMID 37895049, 2023). "In this study, the GnRH1, GnRHR, KISS1, KISS1R, TAC3 and TAC3R genes were analyzed in two unrelated nIHH patients successfully treated for infertility." (PMID 27544332, 2016).
endometriosis (275 papers, 2010 to 2026). The growth of functional endometrial tissue in anatomic sites outside the uterine body. "GNRH1, PGR, TNF, CYP19A1, and IL6 were mentioned with the highest frequencies in endometriosis-related articles." (PMID 34917684, 2021).
prostate carcinoma (270 papers, 1990 to 2026). A carcinoma that arises from epithelial cells of the prostate gland. "Some have found no clear association, while others have observed gender differences in bladder cancer prognosis or suggested that GNRH1 is a prognostic factor for the spread of tumor cells or cell cycle in breast and prostate cancers." (PMID 40096084, 2025). "In ovarian, endometrial, mammary, and prostate cancers significant level of GNRH1 expression was also detected and the agonists of GNRH1 have been shown to inhibit proliferation and stimulate apoptosis of ovarian and endometrial carcinoma cells." (PMID 21827674, 2011). "We studied the association between breast cancer risk and polymorphisms in genes that code for GNRH1 and its receptor (GNRHR) in the large National Cancer Institute Breast and Prostate Cancer Cohort Consortium (NCI-BPC3)." (PMID 19640273, 2009).
breast cancer (165 papers, 1979 to 2026). A primary or metastatic malignant neoplasm involving the breast. "Genetic variants in the gene encoding GNRH1 or its receptor may influence breast cancer risk by modulating production of ovarian steroid hormones." (PMID 19640273, 2009). "Association between GNRH1 htSNPs and breast cancer risk in the BPC3 study." (PMID 19640273, 2009). "Association between GNRH1 haplotypes and breast cancer risk in the BPC3 study." (PMID 19640273, 2009). "In conclusion, we can exclude the possibility that common polymorphisms in GNRH1 and GNRHR confer large or even moderate breast cancer risks in Caucasians." (PMID 19640273, 2009). "We hypothesized that common, functional polymorphisms of GNRH1 and GNRHR could influence breast cancer risk by modifying production of FSH/LH and steroid hormones." (PMID 19640273, 2009). "Based on these results, we conclude that common polymorphisms in GNRH1 and GNRHR do not substantially affect breast cancer risk in Caucasians." (PMID 19640273, 2009).
central precocious puberty (145 papers, 2005 to 2026). "In our study, functional tests indicated that MKRN3 (G93S) is a loss-of-function mutation, which attenuated the inhibition of GnRH1-related signaling, suggesting this mutant can lead to central precocious puberty." (PMID 34421985, 2021).
hypogonadotropic hypogonadism (132 papers, 2005 to 2026). Abnormal ovarian or testicular function due to insufficient hormonal stimulation from the hypothalamic-pituitary axis. "The mutation found in the present study is drastically different than that found in the hpg mouse or in humans with hypogonadotropic hypogonadism due to GNRH1 mutations." (PMID 27355207, 2016). "In addition, humans with hypogonadotropic hypogonadism are characterized by a failure to undergo puberty and have been described to possess one of approximately six different forms of mutations in GNRH1, in which one of the mutational “hot spots” tends to be in the region encoding the decapeptide." (PMID 27355207, 2016). "For instance, these regions contain the gonadotropin releasing hormone receptor (GNRHR) and gonadotropin releasing hormone 1 (GNRH1) genes, both of which are associated with hypogonadotropic hypogonadism and play an important role in reproduction." (PMID 29790964, 2018). "Disturbances in GnRH-1 ns migration, GnRH-1 synthesis, secretion or signaling lead to varying degrees of hypogonadotropic hypogonadism (HH), which impairs pubertal onset and fertility." (PMID 28970231, 2017). "Disturbances either in this migration or in GnRH-1 synthesis, secretion, and signaling lead to hypogonadotropic hypogonadism (HH), which adversely affects normal sexual development, social interactions, fertility and propagation of the species." (PMID 28970231, 2017). "The most obvious candidate gene for patients with hypogonadotropic hypogonadism was GnRH itself after description of the hypogonadal mouse model with homozygous deletion within the GNRH1 gene." (PMID 22229029, 2012). "Lack of GnRH-1 secretion or signaling causes hypogonadotropic hypogonadism (HH), a pathology characterized by delayed or absent pubertal onset and sterility." (PMID 30881290, 2019). "Defective migration of the GnRH-1 neurons to the brain, lack of GnRH-1 secretion or signaling cause hypogonadotropic hypogonadism (HH), a pathology characterized by delayed or absence of puberty." (PMID 30881290, 2019). "The CHH phenotype of our patient, consisting of micropenis, small testes and low LH, FSH and testosterone, cannot be attributed solely to the GNRH1 p.Arg73Ter heterozygous variant, since hypogonadotropic hypogonadism 12 with or without anosmia (MIM Number 614841) is dominantly inherited." (PMID 35805171, 2022). "Genetic screening for mutations in the candidate genes for hypogonadotropic hypogonadism, namely FGFR1, PROK2, PROKR2, GNRH1, GNRH2, was negative." (PMID 25260871, 2014). "Additionally, genetic causes of isolated hypogonadotropic hypogonadism such as KAL1, FGFR1/FGF8, PROKR2/PROK2, CHD7, or GNRH1 gene mutations have not been studied because the patient had a normal puberty and regular menstruation before the amenorrhea." (PMID 26266058, 2015).
hypogonadism (90 papers, 2011 to 2026). A disorder characterized by decreased function of the gonads. "The development and migration of the Gnrh3 neuron system is essential to its proper function as is seen in humans with Kallmann syndrome, in which a cessation of GNRH1 soma/fiber migration and subsequent hypogonadism are observed." (PMID 27355207, 2016).
Kallmann syndrome (83 papers, 2009 to 2026). Kallmann syndrome (KS) is a developmental genetic disorder characterized by the association of congenital hypogonadotropic hypogonadism (CHH) due to gonadotropin-releasing hormone (GnRH) deficiency, and anosmia or hyposmia (with hypoplasia or aplasia of the olfactory bulbs). "Our results challenge previous theories on GnRH-1 neuronal migration mechanisms and provide a new impetus to identify and understand the complex genetic mechanisms causing disorders like Kallmann syndrome (KS) and HH." (PMID 30881290, 2019). "The phenotypic association between anosmia and defective GnRH-1 migration in Kallmann syndrome led to a prevailing model suggesting that migration of GnRH-1 neurons to the brain strictly depends on correct formation of the olfactory/vomeronasal system." (PMID 33871676, 2021). "The gonadotropin‐releasing hormone‐1 (GnRH) system is involved in the development of both the reproductive and olfactory systems, which may contribute to the concomitant reproductive and olfactory dysfunction seen in Kallmann syndrome patients." (PMID 35799980, 2022). "Reproductive disorders such as Kallmann Syndrome, Idiopathic Hypogonadotropic Hypogonadism, Prader-Willi Syndrome, and CHARGE Syndrome, are attributed to disruptions in Gnrh1 gene expression, GnRH neuron signaling, and/or neuronal maturation." (PMID 27389022, 2016).
diabetes (51 papers, 2008 to 2026). "Two studies showed that IgM antibodies against GnRH1 tended to be higher in patients with gastrointestinal complaints related to diabetes mellitus, compared to controls." (PMID 36523699, 2022). "One study found that antibodies against GnRH1, LH, and other related hormones were present more often in patients with diabetes mellitus." (PMID 32075680, 2020). "IgM antibodies against GnRH1, progonadoliberin-2, and GnRH receptors may occur in a subgroup of patients with functional bowel disorders and dysmotility, both in idiopathic forms and when associated with diabetes mellitus, posterior laryngitis, primary Sjögren’s syndrome, or GnRH treatment." (PMID 28638366, 2017). "Serum IgM antibodies against GnRH1, progonadoliberin-2, and GnRH receptors have been described in patients with signs and symptoms of gastrointestinal dysmotility and/or autonomic dysfunction, such as irritable bowel syndrome, enteric dysmotility, diabetes mellitus, and primary Sjögren’s syndrome." (PMID 28638366, 2017).
ovarian carcinoma (50 papers, 2005 to 2025). A malignant neoplasm originating from the surface ovarian epithelium. "GNRH1 expression was detected in two patients with ovarian carcinoma (FIGO II, n = 1; III, n = 1)." (PMID 21827674, 2011). "Treating SKOV-3 cells with either GnRH1 or GnRH2 led to reduced MMP-2 expression and increased secretion of tissue inhibitor of MMP-2 (TIMP2), both important mediators of ovarian carcinoma metastasis." (PMID 38260130, 2023). "Furthermore, GnRH1 and GnRH2 disrupted activation of the phosphatidylinositol-3-kinase (PI3K)/AKT pathway, which promotes proteolysis and invasion in ovarian cancer cells." (PMID 38260130, 2023).
endometrial cancer (45 papers, 2001 to 2026). Primary or metastatic malignant neoplasm involving the endometrium (mucous membrane that lines the endometrial cavity). "Indeed, both low and high affinity binding sites for GnRH1 were detectable in human endometrial cancer cells, implicating the presence of GnRHR1 (high) and GnRHR2 (low)." (PMID 38260130, 2023). "Notably, GnRH2 analogues have a more potent inhibitory effect than GnRH1 on proliferation of endometrial cancer cells." (PMID 38260130, 2023).
osteoporosis (33 papers, 2014 to 2026). A condition of reduced bone mass, with decreased cortical thickness and a decrease in the number and size of the trabeculae of cancellous bone (but normal chemical composition), resulting in increased fracture incidence. "The homozygous variant GNRH1 rs6185 (CC), associated with osteoporosis, was found in four patients, and might be used as prognostic SNP, but this requires additional study." (PMID 41303600, 2025).
Ovarian cyst (27 papers, 2008 to 2025). The presence of one or more cysts of the ovary. "Variants in genes GNRH1 and GNRHR genes have also been identified in a 6.5-year-old girl with ovarian-cyst-derived peripheral precocious puberty." (PMID 36980008, 2023).
congenital hypogonadotropic hypogonadism (26 papers, 2013 to 2026). Congenital hypogonadotropic hypogonadism (CHH) is a rare disorder of sexual maturation characterized by gonadotropin (Gn) deficiency with low sex steroid levels associated with low levels of follicle stimulating hormone (FSH) and luteinizing hormone (LH). "A 28-year-old man with congenital hypogonadotropic hypogonadism (CHH) was found to be heterozygous for the GNRH1 p.R31C mutation, reported in the literature as pathogenic and dominant." (PMID 37372384, 2023). "Mutations of the human GNRH1 gene, encoding a 92 amino-acid pre-pro-GnRH, are a very rare cause of normosmic congenital hypogonadotropic hypogonadism (nCHH)." (PMID 23936060, 2013).
coronary heart disease (23 papers, 2008 to 2025). "Mutations in GNRH1 have been shown to be related to ischemic heart disease, which shows a seasonal pattern." (PMID 36745672, 2023).
hypothyroidism (23 papers, 2011 to 2025). Abnormally low levels of thyroid hormone. "The increase in Kiss1r caused by hypothyroidism may be a compensatory effect of the reduced hypothalamic Gnrh1 expression, although further studies are needed to elucidate this issue." (PMID 37798396, 2023). "However, in the present study, hypothyroidism increased Pdyn expression in the ARC, which is consistent with the reduction in Gnrh1 expression in the POA of these animals." (PMID 37798396, 2023).
cryptorchidism (19 papers, 2011 to 2025). The failure of one or both testes of a male fetus to descend from the abdomen into the scrotum during the late part of pregnancy. "For cryptorchidism, both the androgen receptor and gonadotropin-releasing hormone 1 were predicted." (PMID 21846611, 2011). "Causal P and LP variants were identified in 5 out of 13 patients with a history of cryptorchidism (three in FGFR1, one in ARHGAP5, and one in GNRH1), in 2 out of 8 patients with hearing impairment (CHD7 and FGFR1 genes), and in 2 out of 2 patients with renal agenesis (ANOS1 gene)." (PMID 39308770, 2024).
bladder cancer (17 papers, 2009 to 2026). "In addition, elevated expression of GnRH1 and GnRHR1 in bladder cancer is linked with better survival in men but worse survival in women, suggesting possible regulation of the GnRH1/GnRHR1 system by gonadal steroids in non-reproductive tissues." (PMID 38260130, 2023).
Down syndrome (11 papers, 2022 to 2025). "A mouse model of Down syndrome showed that progressive postpubertal sensory and cognitive deterioration was seen in association with an age-dependent decline in GnRH production, associated with decreased expression of GnRH1 and imbalances in transcription during mini-puberty." (PMID 38436980, 2024).
male infertility (11 papers, 2012 to 2025). The inability of the male to effect fertilization of an ovum after a specified period of unprotected intercourse. "Additionally, our study raises questions about the implications of ESR1 and GnRH1 gene mutations in male infertility, which warrant a more in-depth investigation." (PMID 37895049, 2023).
gynecological cancer (8 papers, 2009 to 2025). "Real time RT-PCR results revealed CGB and GNRH1 genes activity in both tumor tissue and blood of gynecological cancers patients." (PMID 21827674, 2011). "CGB and GNRH1 activity was studied also in blood of gynecological cancer patients and was compared to the control blood of healthy volunteers." (PMID 21827674, 2011). "In this study the presence of cells expressing CGB and GNRH1 in tumor tissue and blood of gynecological cancer patients was confirmed with real time RT-PCR." (PMID 21827674, 2011). "CGB and GNRH1 transcripts were found also in peripheral blood of gynecological cancer patients as well as in blood of healthy volunteers." (PMID 21827674, 2011). "The expression of CGB and GNRH1 was evaluated for gynecological tumor tissue and peripheral blood of patients with gynecological cancer using real time RT-PCR method." (PMID 21827674, 2011). "The aim of this study was to evaluate human chorionic gonadotropin beta subunit (CGB) and gonadoliberin type 1 (GNRH1) expression as markers of tumor cells circulating in peripheral blood of gynecological cancer patients, indicating the metastatic spread of tumor." (PMID 21827674, 2011). "Our study identifies two mRNA markers of gynecological cancers: human chorionic gonadotropin beta subunit (CGB) and gonadotropin releasing-hormone type 1 (GNRH1), which enable detection of circulating tumor cells." (PMID 21827674, 2011).
adrenocortical carcinoma (4 papers, 2012 to 2025). "We found that the higher GNRH1 was expressed, the shorter OS was observed in KIPAN (p = 2.9e-5), KIRC (p = 5.5e-5), LAML (p = 5.4e-3), and ACC (adrenocortical carcinoma) (p = 0.02)." (PMID 35646056, 2022).
cutaneous melanoma (3 papers, 2013 to 2022). A primary melanoma arising from atypical melanocytes in the skin. "On the contrary, a lower expression of GNRH1 was correlated with shorter OS in HNSC (p = 0.02) and SKCM (skin cutaneous melanoma) (p = 0.04)." (PMID 35646056, 2022).
Primary amenorrhea (3 papers, 2017 to 2023). "The two anosmic KS females with a history of primary amenorrhea harbored P/LP variants (in the first case in the GNRH1 gene (with no other accompanying congenital defect), and in the second case in the GNRHR gene), presenting incomplete rotation of the right kidney." (PMID 34198905, 2021).
invasive breast carcinoma (2 papers, 2009 to 2020). A carcinoma that infiltrates the breast parenchyma. "We sequenced exons of GNRH1 and GNRHR in 95 invasive breast cancer cases." (PMID 19640273, 2009).